TRPM2 (transient receptor potential cation channel subfamily M member 2)
Diseases named in the same sentence as TRPM2 in open-access papers (continued):
Sharing a sentence is not in itself a finding about the gene and the disease.
neuroblastoma (continued). "Results demonstrate that TRPM2 expression protects the viability of neuroblastoma through Src, Pyk2, CREB, and MCU activation, which play key roles in maintaining mitochondrial function and cellular bioenergetics." (PMID 30020827, 2018). "In fact, TRPM2-L protected neuroblastoma cells from physiological oxidative stress, and inhibition of TRPM2 in neuroblastoma xenografts significantly reduced tumor growth and increased sensitivity to doxorubicin." (PMID 30020827, 2018). "A protective role of TRPM2 under hypoxia can also be found in neuroblastoma cells, in which activated TRPM2 channels lead to increased expression of superoxide dismutase 2 (SOD2) and reduced ROS levels." (PMID 29772843, 2018). "The roles of Pyk2, CREB, and Src activation and MCU expression in modulation of neuroblastoma cell survival by TRPM2 were investigated." (PMID 30020827, 2018). "Reduced MCU expression in KO cells resulted in lower peak mitochondrial Ca2+ uniporter currents and the amount of calcium transported (current-time integral) measured in neuroblastoma mitoplasts and also observed in mitoplasts from TRPM2 knockout myocytes." (PMID 30020827, 2018). "Inhibition of TRPM2 in neuroblastoma by depletion with CRISPR technology or expression of dominant negative TRPM2-S has been shown to significantly reduce cell viability." (PMID 30020827, 2018). "Evidence increasingly supports the novel therapeutic approach of targeting TRPM2 to reduce tumor proliferation and survival in a number of malignancies, including neuroblastoma." (PMID 30020827, 2018). "TRPM2 is also highly expressed in a number of malignancies, including melanoma, neuroblastoma, lung, and breast cancer, suggesting that it plays a role in promoting tumor growth and preserving viability." (PMID 30020827, 2018). "The second major finding of this work is that Pyk2 is an important modulator of CREB phosphorylation and expression downstream of TRPM2 in neuroblastoma." (PMID 30020827, 2018). "Here, the role of proline-rich tyrosine kinase 2 (Pyk2) in TRPM2 modulation of neuroblastoma viability was explored." (PMID 30020827, 2018). "For example, TRPM2 inhibition in cardiac and neuroblastoma cells resulted in the upregulation of mitophagy." (PMID 26178079, 2015). "TRPM2 Inhibition (chemical/genetic: SiRNA/KO):Breast cancer cells↓Proliferation ↑DNA damage.Neuroblastoma cells ↓Viability↑ROS ↑DNA damage (sensitised to doxorubicin).Leukaemia ↓Proliferation ↑Chemo sensitivity.Ovarian Cancer ↓Cell viability ↓Proliferation↑Apoptosis.PC3 and HeLa↓Cell migration." (PMID 40722879, 2025). "In addition to neuroblastoma cells, recent studies have confirmed similar regulatory mechanisms of TRPM2 in acute myeloid leukemia cells and gastric cancer cells." (PMID 39007141, 2024). "Latest studies reported that TRPM2 was highly expressed on various cancer including bladder, breast, head and neck, lung, pancreatic, prostate, neuroblastoma, which might hint that TRPM2 could promote tumor progression." (PMID 37608401, 2023). "In neuroblastoma cells, Miller’s group showed that inhibition or silencing of TRPM2 decreased hypoxia-inducible factor-1/2 (HIF)-1/2 and its downstream mitochondrial membrane proteins involved in mitophagy (BNIP3), ROS-scavenging (SOD1/2), and ATP synthesis (ETC., complexes)." (PMID 37576339, 2023). "TRPM2 has been revealed to cause neuroblastoma proliferation which is a non-CNS tumor of childhood as well as chemotherapy sensitivity." (PMID 37337283, 2023). "Down-regulation of TRPM2 expression or function contributes to decreased cancer cell proliferation and survival in many malignancies, such as breast, gastric, pancreatic, neuroblastoma, T-cell and acute myelogenous leukemia, and clear cell renal cell carcinoma." (PMID 37569287, 2023). "In neuroblastoma, cell proliferation is reduced following deletion of TRPM2, suggesting that TRPM2 may be involved in modulation of cell cycle, which is explored here." (PMID 35428820, 2022).
neuroblastoma (continued). "Because TRPM2 deletion results in reduced cell proliferation, survival after doxorubicin treatment, and increased ROS levels which damage DNA, here we investigated the role of TRPM2 in regulation of cell cycle and DNA repair in neuroblastoma cells." (PMID 35428820, 2022). "Here, high TRPM2 expression was associated with significantly poorer outcome in Stage 4 non-MYCN amplified neuroblastoma patients using three publicly available databases." (PMID 36446940, 2022). "High TRPM2 expression significantly enhanced expression of α1, αv, β1 and β5 integrins in the membrane of neuroblastoma cells and integrin complex formation, through transcriptional mechanisms including increased HIF-1α, E2F1, and FOXM1, resulting in promotion of migration and invasion." (PMID 36446940, 2022). "Here, the role of TRPM2 in migration and invasion of neuroblastoma cells was examined." (PMID 36446940, 2022). "Decreased expression and activity of MCU in neuroblastoma cells with TRPM2 deletion may contribute to reduced cell cycle progression during G1/S and G2/M through inability to meet increased energy requirements." (PMID 35428820, 2022). "High expression of TRPM2 in neuroblastoma was demonstrated previously." (PMID 36446940, 2022). "In Stage 4 non-MYCN amplified neuroblastoma patients, high TRPM2 expression is associated with worse outcome." (PMID 36446940, 2022). "To identify mechanisms involved in the increased proliferation and reduced doxorubicin sensitivity of neuroblastoma cells with TRPM2 expression compared to cells with TRPM2 deletion, the focus of this manuscript, we first examined genes involved in cell cycle progression." (PMID 35428820, 2022). "In addition, the authors found that TRPM2 downregulation sensitized GC cells to paclitaxel and doxorubicin, which was consistent with the results of neuroblastoma studies." (PMID 33856653, 2021). "In neuroblastoma, Pyk2 may also play an important role as it was shown that TRPM2 expression increases the viability of neuroblastoma through a pathway involving Pyk2 activation." (PMID 34690733, 2021). "However, the results of our previous study indicated that RSV modulates mitochondrial biogenesis and apoptosis in DBTRG neuroblastoma cells via upregulation of TRPM2 channel activation and ROS generation during HYPX24." (PMID 32296107, 2020). "Investigations of other tumor’s entities indicated that NOX4-derived ROS may limit tumor progression (liver carcinoma) and that TRPM2 overexpression may enhance induction of cell death by H2O2 (neuroblastoma)." (PMID 31671815, 2019). "Neuroblastoma cell lines and xenografts in which TRPM2 was depleted with CRISPR were utilized." (PMID 31575956, 2019). "Inhibition of TRPM2 results in reduced mitochondrial function and cellular bioenergetics, increased mitochondrial reactive oxygen species (ROS), and impaired survival in ventricular myocytes isolated from both global and cardiac-specific TRPM2 knockout hearts and in neuroblastoma cells." (PMID 30020827, 2018). "The decrease in CREB may contribute to impaired mitochondrial function, including reduced oxygen consumption rate (OCR) and ATP production observed in neuroblastoma cells in which TRPM2 was inhibited." (PMID 30020827, 2018). "Previously, depletion of TRPM2 with CRISPR technology or inhibition with a dominant negative isoform was found to significantly impair neuroblastoma cell survival and tumor growth through modulation of mitochondrial function, mitochondrial calcium uptake, ROS production, and cellular bioenergetics." (PMID 30020827, 2018). "Recent publications demonstrated that TRPM2 channels are highly expressed in many cancers, including melanoma, breast cancer, prostate cancer, tongue cancer, and neuroblastoma, suggesting that TRPM2 may promote cell survival." (PMID 30020827, 2018). "In neuroblastoma cells, TRPM2 depletion leads to a suppressed HIF-1α signaling." (PMID 29772843, 2018).
neuroblastoma (continued). "In neuroblastoma cells in which TRPM2 was depleted with CRISPR, both the abundance of phosphorylated Pyk2 (group × exposure time interaction effect, P = 0.0025) and Pyk2 expression (group × exposure time interaction effect, P < 0.0001) were significantly reduced with doxorubicin exposure." (PMID 30020827, 2018). "Of notice, a recent study reports that genetic depletion of the TRPM2 expression in human neuroblastoma SH-SY5Y cells led to an increased mitochondrial ROS level as well as reduced cell proliferation, although it was unclear regarding the implication to ROS-induced cell death." (PMID 29311807, 2017). "Furthermore, a recent study demonstrated that RNAi knockdown of TRPM2 led to decreased growth of human xenograft neuroblastoma tumors in athymic nude mice, which thus demonstrated that TRPM2 modulates tumor growth in neuroblastoma." (PMID 26178079, 2015). "The emergence of evidence has revealed that TRPM2, a highly Ca2+ permeable cation channel, acts as a regulator in cancer growth and survival, and is correlated with poor prognosis in patients with breast, gastric, pancreatic, prostate, head and neck cancers, melanoma, and neuroblastoma." (PMID 37569287, 2023). "TRPM2 promotes migration and invasion in neuroblastoma cells with high TRPM2 expression through modulation of integrins together with enhancing cell survival, negatively affecting patient outcome and providing rationale for TRPM2 inhibition in anti-neoplastic therapy." (PMID 36446940, 2022). "Furthermore, inhibition of TRPM2 expression or function decreased growth and invasion of various cancer cells, including breast, gastric, pancreatic, prostate, head and neck, melanoma, neuroblastoma, leukemia, and lung cancers." (PMID 32575381, 2020). "Consistent with this view, the TRPM2 channel has been found to be highly expressed in numerous cancers including bladder, breast, head and neck, lung, pancreatic, prostate, melanoma, and neuroblastoma, among which most studies were focused on the neuroblastoma." (PMID 33092205, 2020). "Experimental evidence from β-cells, neuroblastoma cells, and HEK293 cells conditionally expressing TRPM2 channels supports NOX-2 involvement in TRPM2-mediated oxidative damage." (PMID 40867637, 2025). "Mitochondrial role expressed through oxygen intake amounts and ATP assembly was considerably declined in TRPM2 diminished cells as well as COX 4.1 and 4.2 expression and BNIP3 were lowered, which was described in neuroblastoma." (PMID 37337283, 2023). "Because ROS were increased in neuroblastoma cells depleted of TRPM231, mitochondrial ROS were quantitated in TRPM2-depleted myeloid leukemia cells using MitoSOX Red and confocal microscopy." (PMID 32312983, 2020). "The role of TRPM2 in generation and reduction of these cofactors was examined in SH-SY5Y neuroblastoma cells following depletion of TRPM2 with CRISPR/Cas9 technology (KO)." (PMID 31575956, 2019). "TRPM2 opening modulates the hypoxia-inducible transcription factor 1/2α (HIF-1/2α) signaling cascade, including proteins involved in oxidant stress, glycolysis, and mitochondrial function in neuroblastoma xenograft models." (PMID 37892239, 2023). "The possibility that an interaction between TRPM2 and integrins has a role in increased migration or invasion in neuroblastoma was considered, but in our model, integrins with elevated expression did not co-immunoprecipitate with TRPM2." (PMID 36446940, 2022). "In Stage 4 MYCN amplified neuroblastoma patients, TRPM2 expression did not correlate significantly with outcome, possibly because MYCN itself transcriptionally regulates expression of many oncogenic proteins including FOXM143." (PMID 36446940, 2022). "Our data suggest that targeting TRPM2 may be a novel approach to reduce FOXM1 expression and increase doxorubicin sensitivity in neuroblastoma and other malignancies." (PMID 35428820, 2022).
neuroblastoma (continued). "Similar observations were made with HEK293 cells engineered to express TRPM2 channels (but not with HEK293 cells lacking TRPM2 expression) upon exposure to H2O2 stress and neuroblastoma cells exposed to the Parkinsonian toxin MPP+ (1-methyl-4-phenylpyridinium)." (PMID 40867637, 2025). "Increased TRPM2 in tumors may be both a driver of high FOXM1 and the embryonic stem cell program seen in non-MYCN amplified Stage 4 neuroblastoma patients, contributing to increased metastasis and worse outcome." (PMID 36446940, 2022). "In Stage 4 neuroblastoma patients without MYCN amplification, high TRPM2 expression correlated with worse patient event free survival compared to patients with low TRPM2 levels 40,42, suggesting that in this subgroup TRPM2 has an important role in modulating metastatic and/or refractory disease." (PMID 36446940, 2022).
diabetes (32 papers, 2011 to 2026). "Research indicates that dysfunctional or dysregulated TRPM2 function has been associated with a range of pathological conditions, including neurodegenerative diseases and diabetes." (PMID 39007141, 2024). "There are only a few studies that demonstrate changes in TRPM2 channel expression and/or function associated with diabetes and obesity." (PMID 33716794, 2021). "The authors suggest that ROS production induced by diabetes is able to activate the transient receptor potential cation channel (TRPM2) in DRG neurons, which represents the possible cause of the onset of diabetic neuropathic pain." (PMID 30551603, 2018). "In streptozotocin (STZ)-induced rodent models of diabetes have confirmed this phenomenon, showing extensive loss of pancreatic β-cells and significantly elevated fasting blood glucose levels in mice, which are ameliorated in TRPM2 KO mice." (PMID 39007141, 2024). "Therefore, regulating the function of TRPM2 in endothelial cells may be a new target to aim for preventing diabetes-related vascular ED caused by oxidative stress." (PMID 36421426, 2022). "In particular, we examine the accumulative evidence that supports the role of TRPM2-mediated Ca2+ signaling in endothelial cell dysfunction caused by various oxidative stress-inducing factors that are associated with tissue inflammation, obesity and diabetes, as well as air pollution." (PMID 34063677, 2021). "In this section, we discuss studies that show a role for TRPM2-mediated Ca2+ signaling in ROS-induced disruption of endothelial function by diverse oxidative stress-inducing pathological factors associated with inflammation, obesity, diabetes, and air pollution." (PMID 34063677, 2021). "The suggested roles of TRPM2 in insulin secretion from pancreatic β-cells and chemokine production in monocytes imply that alteration in expression and function of TRPM2 may increase susceptibility to diabetes and inflammatory disease." (PMID 21291387, 2011). "Supporting in vivo relevance, rodent models of high-fat diet-induced obesity/diabetes showed that genetic knockout of Trpm2 prevented hyperglycaemia, preserved mitochondrial function, and attenuated weight gain." (PMID 40722879, 2025). "The current indication focused the attention on a key function of TRPM2 in the pathophysiology of diabetes and further metabolic disorders such as obesity." (PMID 41009007, 2025). "Similar anti-apoptotic and antioxidant effects of RESV were noted on diabetes mellitus-mediated oxidative retinopathy in mice through TRPM2 channel regulation." (PMID 38976129, 2024). "Diabetes reinforced oxidative stress-induced TRPM2-mediated Ca2+ influx and its control by N-acetylcysteine in rat dorsal root ganglion and brain." (PMID 38308007, 2024). "In consideration of the vital role of TRPM2 in cardiovascular disease and diabetes, we propose the potential of targeting TRPM2 channel as a novel therapeutic strategy for DCM." (PMID 38308007, 2024). "According to the findings, in the DRGs of mice and rats with diabetes mellitus, injections of antioxidants such as selenium, melatonin, and Noopept reduced the oxidant, TRPM2, TRPM7, and TRPV1 stimulator effects of STZ." (PMID 38976129, 2024). "Accumulating evidence has shown that TRPM2 plays a key role in mitochondrial dysfunction in many pathological processes such as Alzheimer's disease, stroke, inflammation, and diabetes." (PMID 37275121, 2023). "Activity of TRPM2 ion channel and ROS are synergistic and mutually reinforcing processes in ECs during diabetes aggravating SCI." (PMID 37215981, 2023). "But overall, the effect of diabetes alone on oxidative stress or TRPM2 expression is more similar to those in SCI alone." (PMID 37215981, 2023). "Here, we build a T1D combined with SCI rat model and try to explore the regulatory role of TRPM2 ion channel on BSCB destruction during diabetes combined with SCI recovery." (PMID 37215981, 2023).